CD4 (CD4 molecule)
Diseases named in the same sentence as CD4 in open-access papers (continued):
Sharing a sentence is not in itself a finding about the gene and the disease.
rheumatoid arthritis (continued). "In a mouse model of rheumatoid arthritis induced by ursodeoxycholic acid, the overexpression of AMPK and p38 in CD4 + T cells inhibited Th17 differentiation by naive T cells, thereby suppressing the inflammatory response." (PMID 39533324, 2024). "Jusvinza is an immunomodulatory drug composed of an altered peptide ligand (APL) designed from a novel CD4+ T cell epitope of human heat shock protein 60 (HSP60), an autoantigen involved in the pathogenesis of rheumatoid arthritis (RA)." (PMID 39767648, 2024). "In our previous work, comparing two types of early untreated rheumatoid arthritis patients, we identified a somewhat similar CD27+ CD4 T cell subset." (PMID 37306812, 2023). "Both CD4+ and CD8+ TEMRA are known to accumulate in the aging process and pathological conditions such as arthritis rheumatoid and persistent viral infection." (PMID 36817441, 2023). "In addition, we analyzed the expression of NTAL in primary CD4+ T cells from healthy donors and Rheumatoid Arthritis (RA) patients." (PMID 36902005, 2023). "Despite the report of an imbalance between CD4+ T helper (Th) cell subsets in rheumatoid arthritis (RA), patient stratification for precision medicine has been hindered by the discovery of ever more Th cell subsets, as well as contradictory association results." (PMID 37215131, 2023). "Boosting eEF2K levels in CD4+ T cells to curtail the proinflammatory microenvironment could potentially usher in a novel approach for the prevention and treatment of inflammatory conditions, such as rheumatoid arthritis, multiple sclerosis, and ulcerative colitis." (PMID 37875468, 2023). "Similarly, in the inflamed synovial joint of rheumatoid arthritis (RA) patients, cDC1s were found to be enriched and capable of activating CD4+ and CD8+ T cells, contributing to inflammation." (PMID 36685500, 2022). "In patients with rheumatoid arthritis, it was observed that circulating CD16+ monocyte subsets revealed the potential to promote Th17 cell expansion from peripheral blood memory CD4+ T cells in vitro." (PMID 35740384, 2022). "In a mouse model for rheumatoid arthritis, CCR7+ CD4+ T cells accumulated and homed to lymphoid organs where they survived and maintained autoreactivity." (PMID 35544042, 2022). "Notably, in untreated rheumatoid arthritis (RA) patients, the expression of ARID5a in CD4+ T cells is enhanced, whereas treatment with the anti-IL6R antibody tocilizumab results in a decrease in the expression of Arid5a, indicating that the IL-6-ARID5A axis may be involved in the pathogenesis of RA." (PMID 36010693, 2022). "Moreover, we also detected the expression of IL21‐AS1 and IL21 in CD4+ T cells of systemic sclerosis, rheumatoid arthritis (RA) and psoriasis (PSO)." (PMID 36447054, 2022). "As reported in rheumatoid arthritis, proinflammatory cytokines enhance secondary CXCL13 production by reactivating CXCL13-producing CD4 T cells." (PMID 35734177, 2022). "An increased number of premature senescent CD4+CD28- T lymphocytes has been frequently observed in osteolytic diseases, including rheumatoid arthritis, juvenile idiopathic arthritis, ankylosing spondylitis, osteopenia, osteoporosis, and osteomyelitis." (PMID 34341698, 2021). "In rheumatoid arthritis (RA), it has been specifically shown that CD4+CD28null T lymphocytes are significantly increased in the blood and synovial fluid of these patients, and it has been suggested that these cells have an active role in the maintenance of inflammation." (PMID 34202487, 2021). "CD4+ Th cells are important for the tissue destruction observed in various inflammatory and autoimmune diseases such as multiple sclerosis, rheumatoid arthritis (RA), and inflammatory bowel disease (IBD)." (PMID 33917542, 2021). "However, elevated expression of miR-223 in CD68+ macrophages, CD14+ monocytes, and CD4+ T cells from synovium of rheumatoid arthritis (RA) patients was reported." (PMID 34222229, 2021).
rheumatoid arthritis (continued). "Moreover, compared with healthy controls, the CD4+ TSCM of rheumatoid arthritis (RA) patients increased significantly." (PMID 34604060, 2021). "Importantly, the expression of Helios in CD4+ T cells was significantly increased in rheumatoid arthritis (RA) patients who were successfully treated with tocilizumab (TCZ), a humanized anti-IL-6R antibody." (PMID 34257746, 2021). "A previous study has reported that tofacitinib could inhibit the proliferation of CD4+ T cells in rheumatoid arthritis (RA) patients, which may be the main mechanism by which tofacitinib treats RA." (PMID 34394075, 2021). "In contrast, a study in rheumatoid arthritis patients showed that tofacitinib inhibits the secretion of both IL-17 and IFN-γ in anti-CD3/anti-CD28 stimulated CD4+ T cells." (PMID 34020693, 2021). "discussed the intervention of regulatory T cells characterized by the expression of CD4+, CD25+, and Foxp3+ in patients with rheumatoid arthritis." (PMID 33791204, 2021). "In rheumatoid arthritis (RA) patients, BTLA-expressing CD3+/CD4+/CD8+ T cell proportions are remarkably increased, and the swollen joint count is negatively correlated with the percentage of BTLA+CD8+ T cells." (PMID 33859648, 2021). "miR-371b-5p was significantly increased in both CD4+ and CD8+ T cells while miR-5100 expression was increased in CD4+ T cells in SLE patients compared to healthy controls and patients with rheumatoid arthritis (RA)." (PMID 34639078, 2021). "While activation of CD4+ Th1 and impairment of CD4+ Tregs are essential for the pathology of rheumatoid arthritis, the DIME analysis of RA revealed several lymphoid cells such as CD4+ Tregs, CD4+ Th1, NK cells, etc., as the top DACs in the top cluster." (PMID 34108969, 2021). "HAART: highly active antiretroviral treatment, RA: rheumatoid arthritis, TNF-α: tumor necrosis factor-alpha, CD4+ T: cluster of differentiation-4 +T, RNA: ribonucleoprotein." (PMID 33209528, 2020). "In patients suffering from rheumatoid arthritis treated with RTX, a reduction of CD4-cells has been described." (PMID 31947836, 2020). "The CD4/CD8 more than 2.5 indicates that the cellular immune function is in an “overactive” state and is prone to appear autoimmune reactions such as rheumatoid arthritis as well as type I diabetes." (PMID 33101021, 2020). "In rheumatoid arthritis, CCR4 plays a critical role in CD4+ T cell migration to the synovium contributing to joint inflammation." (PMID 32973504, 2020). "The subset that scored the highest in innateness, CD4+HLA-DR+CD27− T cells, are the precise subset that is most expanded in rheumatoid arthritis and correlate with treatment response." (PMID 30737409, 2019). "Although not shown in this study, it has been reported that TSPO is as well expressed by CD4+ lymphocytes in EAE, as it is in humans and in a model of rheumatoid arthritis." (PMID 30696113, 2019). "Patients with long-term, treated, rheumatoid arthritis (RA) show abnormalities in their circulating CD4+ T-lymphocytes, but whether this occurs in recently diagnosed naïve patients to disease-modifying drugs (DMARDs) is under discussion." (PMID 31405169, 2019). "In rheumatoid arthritis (RA) patients, culturing of CD4+CD28+ T cells with TNFα results in the reduction of CD28 expression on CD4 cells and generation of the CD4+CD28null subset by influencing CD28 gene transcription." (PMID 29546695, 2018). "Regulatory T cells (Tregs, CD4+CD25+Foxp3+) exhibit immune suppressive effects in the immune system, regulate bone remodeling, and are closely linked to skeletal-related disease, such as osteoporosis and rheumatoid arthritis (RA)." (PMID 29675436, 2018). "Finally, the protective effect of collagen/α2β1 integrin on MTX-induced apoptosis also occurs in memory CD4+ T cells isolated from rheumatoid arthritis (RA) patients suggesting its clinical relevance." (PMID 30374344, 2018).
rheumatoid arthritis (continued). "The present study established an experimental model of IL-17-producing cells polarized from human CD4+ cells and broadened our knowledge of the mechanism of TNF-α inhibitors in rheumatoid arthritis treatment." (PMID 27926504, 2017). "Moreover, CD4+CD28− T cells are significantly increased in rheumatoid arthritis (RA) and other autoimmune conditions." (PMID 28303136, 2017). "In this study, we observe the percentage of GM-CSF+ CD4 and CD8 T cells in spondyloarthritis to be significantly higher than rheumatoid arthritis (RA), as well as healthy controls." (PMID 29142230, 2017). "We report the case of a 47-year-old female patient with rheumatoid arthritis and HIV infection presenting with a 3-week history of a painful swollen knee, increased serum inflammatory markers, and a low CD4 lymphocyte count." (PMID 27366339, 2016). "As reported in rheumatoid arthritis, proinflammatory cytokines enhance secondary CXCL13 production from reactivated CXCL13‐producing CD4+ T cells." (PMID 26541894, 2016). "Since lipid compounds are known to modulate the function of CD4+ T-cells and macrophages, we hypothesize that altered levels of serum non-esterified fatty acids (NEFA) may underlie rheumatoid arthritis (RA) pathogenesis." (PMID 27487156, 2016). "It has been reported that tolerogenic dendritic cells (tDCs) generated from monocytes of patients with multiple sclerosis, type 1 diabetes (T1D), or rheumatoid arthritis (RA) are able to induce a stable hyporesponsive state in CD4+ T cells in an antigen-specific manner." (PMID 26441992, 2015). "Accumulating data implicate the CD4+ T cell subset (Th17 cells) in rheumatoid arthritis (RA)." (PMID 24513269, 2014). "Here, we studied genetic and cellular traits of CD4-positive effector memory T (CD4+ TEM) cells, which are particularly important in the onset of rheumatoid arthritis, celiac disease, and type 1 diabetes." (PMID 24968232, 2014). "In the synovial fluid from patients with rheumatoid arthritis, an elevated proportion of IFN-γ producing CD4+ and CD8+ T cells have been reported." (PMID 25501574, 2014). "In fact, due to its functional significance as a co-receptor, CD4 has been clinically tried as a major target in T cell-targeted therapies for the treatment of T cell-mediated autoimmune diseases such as rheumatoid arthritis (RA)." (PMID 23700441, 2013). "Studies have shown the importance of CD4+ T cells, B cells, and cytokines such as RNAKL, TNFα, IL-1, and IL-17 in the pathogenesis of rheumatoid arthritis." (PMID 24222748, 2013). "CD4+CD161+ T cells were readily detected in synovial tissues from both early and late-stage rheumatoid arthritis." (PMID 24223933, 2013). "Interestingly, DCIR is expressed on the surface of CD4+ T cells in rheumatoid arthritis (RA) patients before glucocorticoid treatment and a decrease of DCIR expression was seen with disease improvement." (PMID 21085612, 2010). "In addition, ectopic expression of FoxP3 conveys a Treg phenotype to CD4+ T cells, lending itself to therapeutic use in the prevention of rheumatoid arthritis (RA)." (PMID 20384988, 2010). "For instance, Tregs derived from patients with rheumatoid arthritis (RA) are defective in their ability to suppress cytokine production and to convey a suppressive phenotype to CD4+ effector T cells, which was at least partly restored upon treatment of TNFα neutralizing therapies." (PMID 19543397, 2009). "Interestingly, in patients with rheumatoid arthritis a high percentage of CD4+ T cells in synovial fluid express CD134 in comparison with peripheral blood T cells, suggesting that auto-aggressive CD4+ T cells may be transiently marked by surface expression of CD134 in arthritis too." (PMID 15899047, 2005). "Comparable findings have been reported in rheumatoid arthritis, where EZH2 downregulation has been reported in naïve CD4 T cells, indicating that epigenetic abnormalities in immune cells may be an early event in chronic inflammatory diseases." (PMID 41518566, 2026).
rheumatoid arthritis (continued). "SARS‐CoV‐2 vaccination in rheumatoid arthritis leads to the development of CD4+ and CD8+ spike‐specific T cell memory, regardless of immunosuppressive therapies, and the number of vaccine injections." (PMID 41416941, 2025). "Similarly, a study in the United States found that the TL in CD4+ and CD8+ T-cell subsets was significantly reduced in patients with rheumatoid arthritis compared with healthy controls." (PMID 40907117, 2025). "Phase II trials for the CD4-IgG1 antagonist tregalizumab, originally planned for the indication rheumatoid arthritis, were discontinued due to a lack of efficacy in bronchial asthma." (PMID 39600395, 2024). "In a randomized controlled trial (RCT) in patients with rheumatoid arthritis, a negative correlation was observed between baseline CD4 Treg and Disease Activity Score-28 joints (DAS28; r = −0.625, p<0.001)." (PMID 39483464, 2024). "Furthermore, rosmarinic acid induced the apoptosis of T cells, including CD3+CD25+ and CD4+CD25+ T cells, in rheumatoid arthritis patients via the mitochondrial pathway, thereby alleviating RA." (PMID 38542838, 2024). "However, in CD4 + T cells and CD8 + T cells, we additionally observed specific enrichment for the immune-mediated diseases (rheumatoid arthritis (RA), Crohn’s disease (CD), multiple sclerosis (MS) and hay fever)." (PMID 37072791, 2023). "Moreover, 50, 100, and 200 μg/mL OLE promote the expansion of CD4+CD25+FoxP3+ T regulatory cells (Tregs) in both healthy controls and rheumatoid arthritis patients after 24 h." (PMID 37446206, 2023). "In patients with chronic inflammation, such as rheumatoid arthritis, the PKM2/STAT3 signaling pathway participates in the production of IL-17 and fatty acids in CD4+ T cells under a lactate accumulation environment, thereby causing retention of CD4+ T cells and promoting disease progression." (PMID 35967360, 2022). "Circulating CD4+ T follicular helper (Tfh) cell responses of severe acute respiratory syndrome coronavirus 2 (SARS-CoV-2) mRNA vaccinated SARS-CoV-2 experienced rheumatoid arthritis using methotrexate (RA-MTX) and multiple sclerosis using ocrelizumab (MS-OCR) patients." (PMID 35838348, 2022). "In contrast, CD19+CD24hiCD38hi B cells from patients with rheumatoid arthritis failed to convert CD4+CD25− T cells into functionally suppressive Tregs or to curb Th17 development; however, they maintained the capacity to inhibit Th1 cell differentiation." (PMID 34102006, 2021). "Here we hypothesized enrichment of CD146+IL-17+ memory T cells in PsA synovium and studied the association of CD146 expression and CD4+IL-17+ activated memory (CD11a+CD45RO+) T cells in synovial fluid and blood of PSA, rheumatoid arthritis (RA, a positive control) and osteoarthritis (OA) patients." (PMID 34491483, 2021). "Also, HSP40 has been shown to exert immunoregulatory function in patients with rheumatoid arthritis (RA), where HSP40 represses the proliferation of CD4+ and CD8+ T cells and stimulates the secretion of IL-10 by PBMCs." (PMID 33023034, 2020). "With naïve T cells constituting the largest T cell compartment, this means that the absolute increase in the activated CD4+CD151+ T cell population observed in HIV/ART patients, as for rheumatoid arthritis patients, is mostly driven out of the naïve T cell compartment." (PMID 32978478, 2020). "Natural killer cells in rheumatoid arthritis patients were reduced upon IFX therapy and in ulcerative colitis patients derived cells, IFX treatment decreased the proliferation of CD4+ and CD8+ T-cells as well as their secretion level of IFNγ and TNFα, among other cytokines." (PMID 31272418, 2019). "Finally, to determine the influence of the inflammatory environment in the joints of patients with rheumatoid arthritis (RA) on mitochondrial transfer from MSCs to T cells, we compared mitochondrial transfer from RA synoviocytes and healthy BM-MSCs to CD4+ T cells." (PMID 31370879, 2019).
rheumatoid arthritis (continued). "Here, we show that patients with newly diagnosed rheumatoid arthritis have expanded CD8+ T-cell clones; in 20% (5/25) of patients CD8+ T cells, but not CD4+ T cells, harbour somatic mutations." (PMID 28635960, 2017). "A low CD4 count was more often seen in patients with rheumatoid arthritis: 3 (75%) compared to 22 (16%) of patients without rheumatoid arthritis (Fisher’s exact test p = 0.017)." (PMID 29371544, 2017). "Moreover, in rheumatoid arthritis patients, it has been shown an increase of CD161+CD4+ T-cells, but a decrease of CD161+ DN T-cells that was associated with disease activity and inflammation." (PMID 28626460, 2017). "Significant peripheral blood CD4+ T-cell depletion has been observed after a first cycle of rituximab, a monoclonal antibody directed against the CD20 antigen, which is currently used in rheumatoid arthritis." (PMID 27793209, 2016). "The changes in peripheral numbers of CD4+CD161+ T-cells in seropositive arthralgia and early rheumatoid arthritis and the enrichment of these cells at the level of the joint predict a role for CD4+CD161+ T-cells in the early immune events leading to clinical synovitis." (PMID 24223933, 2013). "Previous studies have linked CXCR6 expression by CD4+ and CD8+ T cells to IFN-γ but not IL-4 expression in graft-versus-host-induced hepatitis and rheumatoid arthritis." (PMID 23840334, 2013). "In Rheumatoid arthritis, a subset of in vitro-generated CD8+ Tregs exhibited immuno-regulatory roles, tolerized APCs, inhibited the priming of naïve CD4+ T cells, suppressed memory CD4+ T cells, and prevented the onset of the anti-inflammatory cascade in synovial lesions." (PMID 23133648, 2012). "It has been shown that TL1A (TNF-like cytokine) synergizes with IL-12 plus IL-18 in inducing IFN-γ by CD4+ T cells, and TL1A production by immune complex-stimulated monocytes may be involved in the pathogenesis of rheumatoid arthritis." (PMID 21572994, 2011). "Rheumatoid arthritis (RA) exhibits diverse synovial immunopathology, such as ACPA-driven recognition of citrullinated peptides and CD4+ responses biased towards Th1/Th17." (PMID 41559435, 2026). "Rheumatoid arthritis (RA) is an autoimmune disease of unknown etiology, and one of the major causes of its development is a decrease in the ability of Treg to block the production of interferon γ (IFN ⁃ γ) and tumor necrosis factor α (TNF ⁃ α) by CD4 + CD25 + T cells." (PMID 40103816, 2025). "Besides, CD4+ IL-21+ cells sorted from the synovial fluid can induce fibroblast-like synovial cells to secrete MMP-1 and MMP-3, which promote inflammation and joint pathological changes in patients with rheumatoid arthritis." (PMID 37628716, 2023). "CD4+ CTLs are not specific to IgG4-RD and also expand in the diseases of inflammatory bowel disease, systemic sclerosis, and rheumatoid arthritis, suggesting that these cells may play a role in the process of chronic inflammation and fibrotic disorder." (PMID 35432312, 2022). "Importantly, in untreated rheumatoid arthritis (RA) patients, expression of Arid5a in CD4+ T cells is increased, whereas treatment with the anti-IL-6 receptor antibody tocilizumab is associated with decreased Arid5a expression, indicating that the IL-6-ARID5a axis may be involved in RA pathogenesis." (PMID 36408139, 2022). "In rheumatoid arthritis (RA), one of the most frequently occurring chronic inflammatory diseases, LSD1 acts as a positive regulator of CD4+ T cell activation." (PMID 34082769, 2021). "It is interesting to remark that exosomes produced by synovial fibroblasts from patients developing rheumatoid arthritis (but not from healthy controls) contain membrane-bound TNFα CD4+ T lymphocytes are a major cell population in the inflammatory infiltrate of rheumatoid arthritis patient joints." (PMID 32290050, 2020).